TACR1 (tachykinin receptor 1)
Description:
Receptor for the tachykinin substance P, also able to bind and respond to tachynins neurokinin A/substance K and neurokinin B/neuromedin-K. The rank order of affinity of this receptor to tachykinins is: substance P > neurokinin A/substance K > neurokinin B/neuromedin-K. Substance P binding to its receptor triggers G protein-coupled receptor signaling via activation of phosphatidylinositol hydrolysis by phospholipase C. Substance P binding also triggers signaling via activation of adenylate cyclase activity which results in increased intracellular levels of cyclic AMP (cAMP) (By similarity).
Synonyms: SPR; NK1R; TAC1R; NKIR
Tractability: Small molecule: an approved drug acts on it; a structure with a bound ligand is known; a high-quality ligand is known; it has a high-quality binding pocket; it belongs to a druggable protein family. Antibody: its Gene Ontology location is reachable by antibodies, with high confidence; UniProt places it where antibodies can reach, with medium confidence; UniProt predicts a signal peptide or a membrane-spanning region. PROTAC: a small molecule that binds it is known.
Target class: Membrane receptor; Short peptide receptor (family A GPCR); Neurokinin receptor; Family A G protein-coupled receptor; Peptide receptor (family A GPCR)
Chemical probes: APREPITANT (high quality), CGP-49823, CP-96345 (high quality), L-732138 (high quality), L-733,060, PD081542, PD083938, SUBSTANCE P
Safety:
Unwanted effects reported when the protein is acted on. In parentheses: how it was acted on, where the effect was seen, and who reports it.
bronchoconstriction (activation, acute dosing; nervous system, immune, gonad, gastrointestinal; source: Lynch et al. (2017))
decreased anxiety (inhibition, acute dosing; nervous system, immune, gonad, gastrointestinal; source: Lynch et al. (2017))
decreased blood pressure (activation, acute dosing; nervous system, immune, gonad, gastrointestinal; source: Lynch et al. (2017))
decreased gastric emptying (activation, acute dosing; nervous system, immune, gonad, gastrointestinal; source: Lynch et al. (2017))
decreased gonadotrophic hormones (inhibition, acute dosing; nervous system, immune, gonad, gastrointestinal; source: Lynch et al. (2017))
decreased inflammation (inhibition, acute dosing; nervous system, immune, gonad, gastrointestinal; source: Lynch et al. (2017))
decreased locomotor activity (inhibition, acute dosing; nervous system, immune, gonad, gastrointestinal; source: Lynch et al. (2017))
decreased pain (inhibition, acute dosing; nervous system, immune, gonad, gastrointestinal; source: Lynch et al. (2017))
delayed/absent sexual maturity (inhibition, acute dosing; nervous system, immune, gonad, gastrointestinal; source: Lynch et al. (2017))
increased intestinal transit (activation, acute dosing; nervous system, immune, gonad, gastrointestinal; source: Lynch et al. (2017))
inflammation (activation, acute dosing; nervous system, immune, gonad, gastrointestinal; source: Lynch et al. (2017))
pain (activation, acute dosing; nervous system, immune, gonad, gastrointestinal; source: Lynch et al. (2017))
testicular degeneration (inhibition, acute dosing; nervous system, immune, gonad, gastrointestinal; source: Lynch et al. (2017))
vomiting (activation, acute dosing; nervous system, immune, gonad, gastrointestinal; source: Lynch et al. (2017))
opioid dependence (source: ClinPGx)
Gene: Protein-coding gene on chromosome 2 (75,046,463 to 75,199,520, reverse strand). Ensembl gene ENSG00000115353.
Subcellular location: Cell membrane; Early endosome
Subcellular location (Human Protein Atlas): Basal body; Centrosome; Plasma membrane
Pathways (Reactome):
Signal Transduction: G alpha (q) signalling events; Tachykinin receptors bind tachykinins
Vesicle-mediated transport: Cargo recognition for clathrin-mediated endocytosis; Clathrin-mediated endocytosis
Gene Ontology:
Molecular function: protein binding; substance P receptor activity; tachykinin receptor activity; G protein-coupled peptide receptor activity; G protein-coupled receptor activity
Biological process: adenylate cyclase-activating G protein-coupled receptor signaling pathway; phospholipase C-activating tachykinin receptor signaling pathway; positive regulation of cytosolic calcium ion concentration; positive regulation of flagellated sperm motility; tachykinin receptor signaling pathway; detection of abiotic stimulus; inflammatory response; phospholipase C-activating G protein-coupled receptor signaling pathway; aggressive behavior; angiotensin-mediated drinking behavior; associative learning; behavioral response to pain; eating behavior; G protein-coupled receptor signaling pathway; learning or memory; long-term memory; neuropeptide signaling pathway; operant conditioning; positive regulation of action potential; positive regulation of blood pressure; positive regulation of epithelial cell migration; positive regulation of epithelial cell proliferation; positive regulation of hormone secretion; positive regulation of leukocyte migration; positive regulation of lymphocyte proliferation; and 21 more
Cellular component: plasma membrane; sperm flagellum; sperm head; sperm midpiece; early endosome; cell body; cell periphery; cell surface; dendrite; membrane; postsynaptic membrane
Genetic constraint (gnomAD): Loss-of-function variants: 25 observed, 38.02 expected, observed/expected ratio (o/e) 0.66, 90% interval 0.48 to 0.92. The upper end of that interval is the gene's LOEUF score, 0.92, which puts it in group 3 of 6, group 1 being the genes least tolerant of losing a copy. Missense variants: 478 observed, 551.28 expected, observed/expected ratio (o/e) 0.87, 90% interval 0.8 to 0.94. Synonymous variants: 195 observed, 219.97 expected, observed/expected ratio (o/e) 0.89, 90% interval 0.79 to 1.
Homologues: Orthologues: chimpanzee TACR1 (99% identical), macaque TACR1 (99% identical), rabbit TACR1 (98% identical), dog TACR1 (98% identical), guinea pig TACR1 (97% identical), mouse Tacr1 (95% identical), rat Tacr1 (95% identical), pig TACR1 (91% identical), tropical clawed frog tacr1 (71% identical), zebrafish tacr1a (70% identical), zebrafish tacr1b (67% identical), Caenorhabditis elegans tkr-1 (30% identical). Paralogues in human: TACR3 (58% identical), TACR2 (47% identical), GPR83 (26% identical), NPY1R (24% identical), PRLHR (23% identical), NPY2R (23% identical), NPY4R (22% identical), NPY4R2 (22% identical), GPR75 (19% identical), PROKR2 (19% identical), MTNR1B (19% identical), PROKR1 (19% identical), and 21 more.
Diseases named in the same sentence as TACR1 in open-access papers:
TACR1 is named in the same sentence as 219 diseases in open-access papers, as found by Europe PMC text mining. Sharing a sentence is not in itself a finding about the gene and the disease. The quoted sentences say what the papers report.
breast carcinoma (36 papers, 2010 to 2025). "A study of anthracycline‐based chemotherapy for breast cancer revealed an association between the TACR1 gene and the delayed phase of CINV." (PMID 37676079, 2023). "In breast cancer, sensory nerves release the neuropeptide SP, which binds to tachykinin receptor 1 (TACR1) on cancer cells, inducing cell death and the release of single-stranded RNA." (PMID 40453085, 2025). "A nomogram was constructed using 7 IRGs, including GPR132, IFITM1, IL12B, IL18, IRF7, KCNMB2, and TACR1, to predict the 1-, 2-, and 3-year survival of breast cancer patients." (PMID 37304237, 2023).
glioblastoma (20 papers, 2011 to 2025). The most malignant astrocytic tumor (WHO grade IV). "Knockdown of nine PTGs significantly decreased cell viability, of which lower expression levels of DRD1, DRD2, HTR3A and TACR1 were also associated with better patient survival in The Cancer Genome Atlas (TCGA) glioblastoma cohort." (PMID 39304781, 2024).
Pruritus (19 papers, 2014 to 2026). Pruritus is an itch or a sensation that makes a person want to scratch. "When RVM Tacr1-expressings cells were activated, we observed that itch related behaviors were inhibited, while producing mild mechanical sensitization." (PMID 35972457, 2022). "We next wanted to determine whether activation of RVM Tacr1 expressing neurons would modulate itch related behaviors." (PMID 35972457, 2022). "Since activation of PAG tac1r neurons facilitates itch this implies that activation of RVM Tacr1-expressing neurons may likewise facilitate itch." (PMID 35972457, 2022). "We hypothesized that Tacr1-expressing RVM ON cells exert an inhibitory effect on itch opposite to their pronociceptive action." (PMID 35972457, 2022). "Since activation of RVM Tacr1-expressing neurons inhibited acute pruritogen-evoked scratching behavior, we next wanted to determine whether chronic itch related behaviors would be affected." (PMID 35972457, 2022).
Anxiety (18 papers, 2012 to 2025). Intense feelings of nervousness, tension, or panic often arise in response to interpersonal stresses. "In light of these findings, the possibility that TACR1 polymorphism(s) contribute to co-morbid anxiety in ADHD patients merits further investigation." (PMID 25074741, 2014).
melanoma (15 papers, 2010 to 2023). A malignant, usually aggressive tumor composed of atypical, neoplastic melanocytes. "Interestingly, expression of TACR1 (tachykinin receptor) is downregulated in Slug-overexpressing melanocytes; TACR1 antagonists drive melanoma cell apoptosis, thus Slug overexpression may protect melanocytes from apoptosis." (PMID 22745913, 2012).
neuroblastoma (13 papers, 2010 to 2023). Neuroblastoma (NB) is the most common solid, extracranial childhood tumor. "Our global expression profiling also implicated TACR1 in control of cell cycle progression and apoptosis in neuroblastoma cells, with TACR1 inhibition driving the cell towards apoptosis and cell cycle arrest." (PMID 27888795, 2017). "Encouraged by recent observations of antitumor effects of tachykinin receptor antagonists in various cancer cell lines, we investigated the role of TACR1 in high-risk neuroblastoma and explored whether targeting TACR1 could be a therapeutic option in this disease." (PMID 27888795, 2017). "The knockdown of RMRP inhibits neuroblastoma xenograft growth by modulating the miR‐206 or TACR1 axis and inactivating the ERK1/2 pathway in vivo." (PMID 35592755, 2022). "Inhibition of ERK1/2 pathway and TACR1 reduces the function of RMRP to promote proliferation in neuroblastoma cells." (PMID 35592755, 2022). "RMRP can interact with miR‐206 in neuroblastoma cells, such as sequestering miR‐206 from TACR1 as a ceRNA for miR‐206, implying that RMRP regulates the miR‐206/TACR1 axis to play an oncogenic role in neuroblastoma gene action." (PMID 35592755, 2022). "TACR1 protein was expressed in all human neuroblastoma cell lines assessed, although expression levels varied between cell lines, with SY5Y expressing only low levels and IMR5 strongly expressing TACR1." (PMID 27888795, 2017). "All neuroblastoma cell lines tested exhibited a concentration-dependent reduction in cell viability in response to TACR1 inhibition, although sensitivity varied strongly among cell lines." (PMID 27888795, 2017). "To assess the effect of TACR1 inhibition on neuroblastoma cell viability, we treated cells in vitro with the water soluble aprepitant analog, fosaprepitant, and assessed cell viability relative to untreated control cultures in MTT assays." (PMID 27888795, 2017). "Together, our data extends previous knowledge about the mitogenic role of TACR1 in neuroblastoma and establishes TACR1 as a novel therapeutic target for neuroblastoma." (PMID 27888795, 2017). "Here, we report that neuroblastoma cell lines express TACR1, and that targeting TACR1 activity significantly reduced cell viability and induced apoptosis in neuroblastoma cell lines." (PMID 27888795, 2017). "Here we show that human neuroblastoma cell lines express TACR1 and that blocking TACR1 activity using fosaprepitant robustly inhibits tumorigenic characteristics in both in vitro and in vivo neuroblastoma models." (PMID 27888795, 2017). "TACR1 expression was examined in a panel of neuroblastoma cell lines as well as fibroblast control cells using western blotting and quantitative RT-PCR." (PMID 27888795, 2017). "TACR1 agonist substance P partially restored neuroblastoma cell viability, consistent with on target activity of fosaprepitant and in line with the previously reported stronger binding affinity of fosaprepitant to TACR1." (PMID 27888795, 2017). "Our results support that inhibiting TACR1 with the antagonist, fosaprepitant, provides a therapeutic effect in a mouse model of neuroblastoma, and present fosaprepitant as a possible clinical avenue for patients with neuroblastomas with high-level TACR1 expression." (PMID 27888795, 2017). "Again, IMR5 cells showed the most pronounced increase in cell death, suggesting that fosaprepitant effects on neuroblastoma cells might be dependent on TACR1 signaling activity." (PMID 27888795, 2017).
neuroblastoma (continued). "Similar to previous reports in other tumor entities, we detected decreased SRC phosphorylation following TACR1 inhibition, indicating that in neuroblastoma TACR1 might at least in part signal through SRC." (PMID 27888795, 2017). "Based on our data as well as previous reports, we conclude that the antitumoral activity of fosaprepitant is, indeed, due to selective TACR1 inhibition, and that TACR1 expression as well as SRC phosphorylation in primary neuroblastoma samples may be predictive for fosaprepitant sensitivity." (PMID 27888795, 2017). "Furthermore, TACR1 overexpression induces the ERK1/2 axis and reverses the effects of RMRP downregulation on neuroblastoma cell growth." (PMID 35592755, 2022).
hepatoblastoma (10 papers, 2016 to 2024). Hepatoblastoma (HB) is a malignant hepatic tumor and is the most common pediatric liver cancer. "It has been shown that the TACR1 expression pattern for hepatoblastoma does not correlate with clinical characteristics." (PMID 35049682, 2021). "Similar to our recent study in hepatoblastoma, we here demonstrated for rhabdoid tumors that the expressions of TACR1 and TAC1 do not seem to correlate to parameters such as stage of disease, gender, and age of diagnosis." (PMID 35049682, 2021).
alcohol dependence (9 papers, 2013 to 2023). Physical and psychological dependence on alcohol. "Sharp and colleagues replicated a significant association with intron 1 TACR1 mutations in BD in the BD with Alcohol dependence subgroup and Alcohol dependence syndrome cases compared to a screened population of healthy controls." (PMID 35893041, 2022). "Sharp and colleagues investigated the association of TACR1 with bipolar disorder (BD), BD comorbid with alcohol dependence, alcohol dependence syndrome (ADS), and attention deficit hyperactivity disorder (ADHD)." (PMID 35893041, 2022). "The same study also reported associations between TACR1 SNPs (rs10490308, rs11688000, rs3771863) and symptoms of alcohol dependence." (PMID 25278825, 2014). "The importance of SP/NK1R system in AUD is supported by the observation of significant associations between the NK1R gene (TACR1; rs6715729 and two haplotypes) and alcohol dependence." (PMID 25278825, 2014). "The tachykinin receptor 1 (TACR1) gene has been reported to be associated with bipolar disorder and alcoholism as well as ADHD." (PMID 24971261, 2013).
lung carcinoma (8 papers, 2015 to 2025). "Only the expression of GPR54 was associated with CD8+ T cell infiltration in lung cancer, although Grin1 (glutamate receptor), Ptger1 (prostaglandin E receptor 1), Hrh2 (histamine receptor), Ghsr (growth hormone secretagogue receptor), and Tacr1 (substance P receptor) were detected." (PMID 35224894, 2022).
Sepsis (8 papers, 2016 to 2024). Sepsis is defined as life-threatening organ dysfunction caused by a dysregulated host response to infection. "More interestingly, Tacr1 has been implicated in several bacterial infections and in sepsis, including P. aeruginosa corneal infection." (PMID 27169516, 2016). "Similarly, genetic deletion of the Tacr1 gene has been shown to result in the improvement of cardiovascular function, the decrease of inflammation, and the mortality of mice with CLP-induced sepsis." (PMID 37047113, 2023).
acute pancreatitis (7 papers, 2012 to 2023). An acute inflammatory process that leads to necrosis of the pancreatic parenchyma. "Similarly, mice with a deficiency in the Tacr1 gene were also protected against acute pancreatitis-related remote lung injuries, including neutrophils infiltration and elevated pulmonary microvascular permeability." (PMID 37047113, 2023). "With regard to leukocytes, neutrophil accumulation was significantly inhibited in Tacr1−/− mice in lung injury induced by immune complexes or acute pancreatitis." (PMID 29459872, 2018).
bipolar disorder (6 papers, 2009 to 2022). A disorder of the brain that causes unusual shifts in mood, energy, activity levels and the ability to carry out day-to-day tasks. "Similarly, there is confirmed association between both TACR1 polymorphism(s) and ADHD with bipolar disorder." (PMID 27097734, 2016).
Obesity (6 papers, 2016 to 2024). Accumulation of substantial excess body fat. "Nevertheless, our findings lead to the prediction that a subset of ADHD patients with TACR1 polymorphism(s), especially males, would tend to have short stature, compared with other subjects, and that the males would have an increased risk of developing obesity when fed a Western diet." (PMID 27462087, 2016). "For example, we observed associations between functionally annotated rare variants in the gene TACR1 and chronic sinusitis, as well as associations between functionally annotated variants in ATF7 and obesity related diagnoses (results not passing multiple burden threshold)." (PMID 29545597, 2018).
colon carcinoma (5 papers, 2010 to 2025). "Increased copy number and mRNA expression levels of TACR1 (encoding for NK‐1R protein) were observed in the two colon cancer datasets, suggesting the potential role of the SP/NK‐1R signaling pathway in the pathogenesis of CRC." (PMID 34605226, 2021).
COVID-19 (5 papers, 2020 to 2023). A disease caused by infection with severe acute respiratory syndrome coronavirus 2. "Based on the beneficial effects of MSCs, the Food and Drug Administration (FDA) has recently approved the first MSC (modulated to express TACR1)-based therapy for COVID-19." (PMID 36230930, 2022).